VEGFB (vascular endothelial growth factor B)
Diseases named in the same sentence as VEGFB in open-access papers (continued):
Sharing a sentence is not in itself a finding about the gene and the disease.
tumor (continued). "Active transport of LCFA across ECs, at least in part through VEGFB-VEGFR1 signaling, fuels tumor cell proliferation while also influencing anti-tumor T cell function." (PMID 39567756, 2025). "The majority of DEGs related to this pathway (ITGAV, KDR, VEGFB, AKT1, VEGFA) were downregulated in tumor cells except for HSBP1 and SHC2." (PMID 39245631, 2025). "In our study, we found that PTGS2 and VEGF signalling pathway genes (VEGFA, VEGFB, KDR, CXCR1 and CXCR2) were upregulated in OSCC tumour tissues compared to their paired normal tissues." (PMID 38426619, 2024). "The risk score strongly correlated with the expression of VEGFA, VEGFB, CD276 and C10orf54, and each immune checkpoint was differentially expressed between normal and tumour samples." (PMID 38613352, 2024). "VEGFB and KDR were observed to have a significantly higher median expression when compared to samples with pN0 in tumour samples with pN3 status." (PMID 38426619, 2024). "To investigate the potential significance of VEGF-B in the immunotherapy of human cancer, we analyzed the relationship between the expression level of VEGFB and tumor progression in human tumor samples using TCGA data." (PMID 39145452, 2024). "The protein expression of angiogenesis-related genes such as CCNE1, a disintegrin and metalloprotease 17 (ADAM17), mevalonate diphosphate decarboxylase (MVD), SMA_MVD, VEGFA, VEGFB, VGFR2, HIF-1α in tumor tissues was explored." (PMID 36959862, 2023). "Stimulating signals involved in tumour angiogenesis, like VEGFA–VEGFR2 and VEGFB–VEGFR1, were observed." (PMID 36588094, 2023). "Focusing on tumor–stromal communication, the authors found that tumor cells expressing vascular endothelial growth factors (VEGFA and VEGFB) can stimulate a subpopulation of endothelial cells through VEGF receptors, FLT143 and beta-1 integrin." (PMID 37353907, 2023). "Our previous study has shown that a peptide reproducing helix α1 of VEGFB can unexpectedly interfere with VEGF binding to VEGFR2 and, consequently, inhibit VEGF-stimulated angiogenesis and tumor growth." (PMID 37375853, 2023). "An antagonist peptide of VEGFA/VEGFB, referred to as VGB3, can recognize and neutralize both VEGFR1 and VEGFR2 on the endothelial and tumoral cells, thereby inhibits angiogenesis and tumor growth." (PMID 34983556, 2022). "In the present study, histidine supplementation in HCC cells reduced the expression of tumor markers related to glycolysis (GLUT1 and HK2), inflammation (pSTAT3), angiogenesis (VEGFB and VEGFC), stem cells (CD133), metastasis (Snail/slug), and cell migration." (PMID 35267513, 2022). "Remarkably, we found that exogenous histidine treatment induced a reduction in the expression of tumor markers related to glycolysis (GLUT1 and HK2), inflammation (STAT3), angiogenesis (VEGFB and VEGFC), and stem cells (CD133)." (PMID 35267513, 2022). "Similar to primary tumor cells, a significant positive Pearson correlation score was also observed for JunB and VEGF, VEGFB, and IGF1 in a selected number of MM cell lines deposited in the CCLE database." (PMID 34007044, 2021). "The half-lives of angiogenic mRNAs, including ENG, EDN1, VEGFB and PDGFC, were reduced approximately 2-fold in Roquin2-overexpressing tumor cells compared to the control group." (PMID 34345214, 2021). "These bevacizumab-adapted cells secrete more VEGFA, VEGFB, VEGFC, and PlGF, which induce migration of tumor cells and angiogenesis of endothelial cells in this medium in comparison with the parental cells." (PMID 32560565, 2020). "Plumbagin, an active compound of this plant, exerts an anti-angiogenesis effect by downregulating the PI3K/Akt, VEGF/KDR, and angiopoietins/Tie2 pathways and factors related with cancer angiogenesis and tumor cells, including bFGF, ET-1, CTFG, and VEGFB." (PMID 30871059, 2019). "For example, promising targets to date are miR-622 that targets the Ku pathway and miR-484 that targets both VEGFB and VEGFR2 pathways as well as tumor vasculature." (PMID 35582723, 2019).
tumor (continued). "It has been reported that VEGFB binds specifically to VEGFR1, which is complex and context-dependent; and that increased VEGFB expression correlates with cancer stage, tumor multiplicity, and vascular invasion in multiple cancers." (PMID 28335793, 2017). "VEGF family members, including VEGFA, VEGFB, VEGFC, and VEGFD, are secreted by autocrine stimulation of tumor cells as well as through paracrine influences of the proangiogenic tumour microenvironment." (PMID 25810565, 2015). "Collectively, these findings suggest that CHPF may act as a tumour promoter in CRC, operating in a VEGFB‐dependent manner and could be a potential target for therapeutic interventions in CRC treatment." (PMID 38775031, 2024). "In this study, a significant increase in PTGS2 with VEGFA, KDR, CXCR1 and CXCR2 expression was observed in tumour samples compared to their paired normal samples, with the exception of VEGFB, whose expression was not statistically significant." (PMID 38426619, 2024). "In addition, VEGFB and VEGFC are part of two signaling pathways with major roles in tumor angiogenesis and lymphangiogenesis." (PMID 38256218, 2024). "Additionally, interface-derived and tumor-derived mast cells had high expression levels of VEGFA and VEGFB genes, suggesting potential functions of promoting angiogenesis." (PMID 37644609, 2023). "The Insulin signaling pathway in group 5 was found to mainly lead to activation of genes involved MAPK signaling and this trend converges with hypoxia signaling input, both leading to the production of VEGFB, VEGFA, PGF, growth factors known to be involved in angiogenesis and tumor invasion." (PMID 35568708, 2022). "In addition, we also analyzed tumor angiogenesis genes, and the results showed that seven tumor angiogenesis genes (HIF1A, PDGFB, NRP1, VEGFB, FGFR1, ROBO1, and SLIT1) had substantially higher expression in the high-risk group compared with the low-risk group." (PMID 35311113, 2022). "We also found that CTLA4 and IDO1, two well‐known immune checkpoints, were significantly higher in both tumor tissues and NATs than in healthy tissues, while the expression levels of VEGFB and LAG3 increased progressively in healthy tissues, NATs and tumor tissues." (PMID 33033616, 2020). "Furthermore, VEGFA, KDR, CXCR1 and CXCR2 were significantly upregulated in tumour samples compared with paired normal samples, except for VEGFB, whose expression was not statistically significant." (PMID 38426619, 2024). "In conclusion, we showed that C-VGB3, which reproduces a binding region of VEGFB, could interfere with the interaction between VEGFA and VEGFR2 and inhibit angiogenesis and tumor growth via suppression of PI3K/AKT/mTOR and PLCγ/ERK1/2 pathways in both endothelial and tumor cells." (PMID 37375853, 2023). "In this study, the expression of VEGFB also gradually increased as the trajectory evolved, and the expression of SPP1, which could promote tumor progression, also increased with the evolution of pseudo time, suggesting that M2 macrophages might promote angiogenesis during the progression of LUAD." (PMID 36046337, 2022). "Similarly, the specific APA modification of VEGFB may be involved in the functional regulation of CPEB1 and CPEB4, further contributing to the tumorigenesis of multiple tumor types, including cervical, ovarian, and glioma cancers." (PMID 32626751, 2020). "In attempt to dissect whether CCL3 influences the tumour milieu, we evaluated the expression of molecules involved in tumour proliferation (EGF, FGF, TGF-β and TNF-α) and angiogenesis (TGF-β1, VEGFa and VEGFb)." (PMID 28881626, 2017). "The importance of FLT1, PGF, VEGFA and VEGFB expression and their functions in MLS/RCLS tumor development remain unclear but our results point out this receptor/ligand system as operational in MLS/RCLS and as such a potential target for intervention in this tumor type." (PMID 20515481, 2010).
tumor (continued). "In contrast, the activity of pathways from macrophages, such as VEGFB to VEGFR1 and TNFSF13B to TNFRSF13B, was reduced in tumors, possibly reflecting adaptive changes in macrophage function under tumor conditions, which could impact immune responses and tumor cell regulation (right)." (PMID 39850883, 2024). "Our data indicate that IDB0076 may also trigger cointernalization of a cognate receptor (VEGFR1 for VEGFB and PlGF2) by inducing cellular internalization of NRP1 and should break the resistance to bevacizumab by blocking these growth factors taking part in tumor angiogenesis." (PMID 32560565, 2020). "Furthermore, quantitative analysis of the RNA levels indicated a reduction of VEGFA (the isoform mainly involved in tumour angiogenesis; Claesson‐Welsh & Welsh, 2013) in ERO1 KO cells under hypoxic conditions, but not that of VEGFB." (PMID 35853086, 2022). "Interestingly, CXCL6 and other ARGs also showed negative correlations with checkpoints like VEGFB, KIR2DL1, LAG3, CTLA4, PDCD1, and IFNG, indicating they may promote immune surveillance and anti-tumor responses." (PMID 40943183, 2025).
cancer (87 papers, 2003 to 2025). A tumor composed of atypical neoplastic, often pleomorphic cells that invade other tissues. "In addition, FGF14-AS2 shows a high correlation with a famous cancer-associated gene VEGFB (PCC = 0.70), which is a member of vascular endothelial growth factor family and dysregulated in many cancers." (PMID 28389669, 2017). "BCAM-induced proteins, previously reported to drive EMT and associated processes such as cell migration in various cancers, include AREG, CXCL1, CXCL10, EDN1, FGF2, TGFβ1 and VEGFB." (PMID 40082910, 2025). "In cancers, VEGFB is reported to be capable of promoting cancer metastasis via non-VEGF-A-dependent mechanisms." (PMID 39119581, 2024). "Expression based on individual cancer stages showed that VEGFA and VEGFB were highly expressed in patients with stage 4 cancer." (PMID 38426619, 2024). "Across the 33 cancers, VEGFB and VEGFD showed the highest and lowest expression levels, respectively." (PMID 37852616, 2023). "In this study, we observed that VEGFB, secreted by both cancer cells and non-cancer cells, was the predominant VEGF subtype in advanced CRC with multiple metastases to the liver, lung, and perienteric lymph nodes." (PMID 37576892, 2023). "A key player in angiogenic signaling in cancer, the vascular epithelial growth factor, VEGFB, was overexpressed in resistant cells." (PMID 37444135, 2023). "Increased RAMP1 expression was strongly associated with the upregulation of lymphocyte activation gene 3 (LAG3), vascular endothelial growth factor B (VEGFB), and cytotoxic T-lymphocyte-associated protein 4 (CTLA-4) across multiple cancer types." (PMID 37796823, 2023). "We then examined the expression of the pro-angiogenic factor VEGF and found that in the Naive sample, cancer cells mainly secreted VEGFB, which was predominantly expressed by the sensitive subset." (PMID 37576892, 2023). "Across multiple cancers, VEGFB was highly expressed in six immune subtypes than other VEGF family genes." (PMID 37852616, 2023). "The immune inhibitor CD276 and VEGFA correlated positively with KIF11 in most human cancer types, but VEGFB correlated negatively with KIF11 in most human cancer types." (PMID 36742345, 2022). "The risk of discarding functional transcripts by relying too heavily on the pLDDT score is well-illustrated by vascular endothelial growth factor B (VEGFB), a growth factor implicated in cancer and diabetes-related heart disease." (PMID 36519529, 2022). "A key regulator of cancer-associated fibroblasts, TWIST1, presented a noticeable focal gain >20%, and a regulator of angiogenesis, VEGFB (vascular endothelial growth factor B), presented a noticeable focal gain >40%." (PMID 33050525, 2020). "Recent studies on VEGFR1 showed that VEGFA, PLGF-2, and VEGFB increase sensitivity to cancer pain through activation of VEGFR1 in peripheral sensory neurons." (PMID 30871059, 2019). "VEGFR1 also has a prominent role in cancer and interestingly, like VEGFB, VEGFA can also signal through this receptor." (PMID 29732375, 2018). "VEGFB is a member of the vascular endothelial growth factor family that mediated angiogenesis in cancer." (PMID 30333226, 2018). "Overall, we measured a reduced expression of VEGFB mRNA in cancer-derived AECIIs when compared to cells derived from normal lungs." (PMID 29137669, 2017). "Expression of VEGFB mRNA was significantly reduced by 2.5-fold in primary AECII derived from cancers as compared to cells derived from normal lungs and VEGFC expression was downregulated in cultured AECII (p value at 0.056)." (PMID 29137669, 2017). "Protein expression of VEGFA and of its receptor VEGFR2 was almost abolished in cancers while VEGFB and VEGFD mRNA expression were significantly reduced." (PMID 29137669, 2017). "In CD133−/EpCAM+ cells significantly altered DNA regions contained factors known to be involved in cancer such as VEGFB and MIR192." (PMID 28347289, 2017).
cancer (continued). "In particular, FLT1 is the main receptor for VEGFB and PlGF induced signaling and is over-expressed in several cancer cells." (PMID 20422012, 2010). "Moreover, hsa-miR-130b-5p targeting VEGFB exhibited a positive correlation with hypoxia in various cancers including BRCA and LUAD." (PMID 37852616, 2023). "For cancer, identified targets include VEGFB, VEGFR2, MAP2, MMP14, HNF1A, TUSC5 and KLF12." (PMID 35356223, 2022). "VEGFB, of which the role in cancer is still understudied, showed a weak correlation (R2 = 0.309)." (PMID 32485981, 2020). "Interestingly, VEGFB in NPC showed similar expression levels among various cancers." (PMID 35439170, 2022). "Targeting VEGFB may be an important therapeutic approach for cancer metastasis." (PMID 30886832, 2019). "Among 60 ICP genes, including 24 immune inhibitors (such as CTLA4, LAG3, or VEGFB) and 36 activators (TNFRSF9, CD28, or TNFRSF9, etc.), we found DHCR7 played roles both in inhibitors and activators of ICP in human cancers." (PMID 41198144, 2025). "Subsequent analysis also demonstrated a clear relationship between GPX4 expression and key immune checkpoints such as VEGFB, TGFB1, CD276, TNFRSF18, and TNFRSF4 across most cancer types." (PMID 41142608, 2025). "Previous studies have documented the biological and clinical significance of VEGF family members (VEGFA, VEGFB, VEGFC, and VEGFD) in lymphangiogenesis and LN metastasis in various cancer types." (PMID 40492378, 2025). "Moreover, studies have shown that the expression of VEGFB is abundant in embryonic and adult muscle tissues, and it could promote endothelial cell proliferation and local vascular growth, which is conducive to the growth and metastasis of malignant tumours." (PMID 38775031, 2024). "Particularly, VEGFB, which is a newly identified target sharing similar structures with VEGFA, exhibited enhanced expression level in cancer cells." (PMID 38944814, 2024). "AKT2 was positively correlated with VEGFB and CD274, among others, highlighting its potential involvement in cancer immunology and therapy resistance mechanisms." (PMID 39063239, 2024). "The expression levels of genes involved in cancer invasiveness (MYC, VEGFB, IL33, PTGS2, and PTGER2) were increased." (PMID 37601099, 2023). "Among Roquin2 targets, we chose four angiogenic genes (ENG, EDN1, VEGFB, and PDGFC) based on two criteria: 1) they are commonly downregulated in different types of cancer cells; and 2) they are among the most affected genes by Roquin2." (PMID 34345214, 2021). "In contrast to the genetic studies with VEGFB suggesting a role for this growth factor in cell survival, genetic manipulation of VEGFR1, particularly sVEGFR1, is seen as an anti-angiogenic cancer therapy." (PMID 29732375, 2018). "Various cancer-related genes were also differentially expressed significantly, including BRAF, BRCA2, VEGFA, VEGFB, RET, PIK3CA, CTNNB1 and GNAS." (PMID 27350898, 2016). "From a pan-cancer perspective, ARPC1A expression was positively correlated with VEGFB and CD276." (PMID 38911374, 2024). "This led to the downregulation of TGFβ-responsive genes, including vascular growth factor A/B (VEGFA/VEGFB), hypoxia-inducing factor 1α (HIF-1α), and thrombospondin 1 (TSP1), all of which play crucial roles in various aspects of cancer progression such as angiogenesis, invasion, and metastasis." (PMID 37894372, 2023). "miR-484 is a key factor in cancer and non-cancerous diseases, and its targets in cancer include VEGFB, VEGFR2, MAP2, MMP14, HNF1A, TUSC5, and KLF12." (PMID 36572856, 2022). "Cancer patients feel severe and constant pain due to the involvement of VEGFA, PLGF-2, and VEGFB." (PMID 30871059, 2019). "Firstly, FOLFOX-Bev treatment may kill sensitive cancer cells that primarily secrete VEGFB, leading to compensatory upregulation of VEGFA in the remaining insensitive cancer cells, which is competitively bound by bevacizumab, thereby dually inhibiting the VEGF pathway." (PMID 37576892, 2023).
cancer (continued). "The CAFDL signature was significantly positively associated with TGFB1, CD276, CD40, VEGFA, VEGFB, etc., but showed significantly negative correlation with immune checkpoints (such as CD274, PDCD1, CTLA4, TIGHT, and HAVCR2) and anti-cancer immune regulators (IFNG, IDO1, and GZMA)." (PMID 35967425, 2022). "We also noted high baseline expression of several other potential therapeutic targets including VEGFB, TGFB3, PDGFB/PDGFRB, FGFR1 and IGF1R in cancers that did not achieve pCR." (PMID 30967156, 2019).
cardiovascular disease (7 papers, 2017 to 2025). "In this regard, VEGFB’s involvement in lipid metabolism and its regulation of mitochondrial dynamics provide new insights into its therapeutic potential in addressing metabolic dysfunctions, in particular ferroptosis induction in MI, that often accompany cardiovascular diseases." (PMID 41148858, 2025).
metabolic disorders (5 papers, 2020 to 2025). "Multiple groups have reported that stimulation of angiogenesis in adipose tissue of obese rodents by increasing angiogenic gene expression (e.g., VEGFA, VEGFB, FLT1, FOXO, Angiopoietin2) not only improves local adipose tissue function, but also counteracts systemic metabolic disorders." (PMID 34660572, 2021).
infection (4 papers, 2011 to 2024). The state of being infected such as from the introduction of a foreign agent such as serum, vaccine, antigenic substance or organism. "In contrast, infection did not significantly impact cellular expression of EGF, FGF2, and VEGFB, and FGF1 expression was not reliably detected." (PMID 31569536, 2019).
neurological disease (3 papers, 2017 to 2025). "Ten proteins showed co-localization with a neurological disease using both plasma protein abundance and plasma mRNA abundance (SIRPA, CTSH and CD33 with AD; and ASF1A, FCRL3, VEGFB, TYMP, PVALB, LMAN2 and CD5 with MS)." (PMID 40037332, 2025).
VEGFB also shares sentences with these, for which no sentence is quoted: diabetic retinopathy (8 papers); diabetic nephropathy (7); heart disease (7); lung carcinoma (7); myocardial ischemia (7); Hyperglycemia (6); cardiomyopathy (5); endothelial dysfunction (5); lung squamous cell carcinoma (5); amyotrophic lateral sclerosis (4); colon carcinoma (4); hemangioma (4); Hepatic steatosis (4); neurodegenerative disease (4); acute myocardial infarction (3); age-related macular degeneration (3); bladder cancer (3); macular edema (3); multiple sclerosis (3); polycystic ovary syndrome (3); prostate carcinoma (3); retinal degeneration (3); sarcoma (3); Alzheimer disease (2); Arrhythmia (2); cerebral artery (2); cutaneous melanoma (2); experimental autoimmune encephalomyelitis (2); Hepatic fibrosis (2); hyperlipidemia (2).
A further 99 diseases each share a sentence with VEGFB in 2 papers or fewer.